RNU4-86P (RNA, U4 small nuclear 86, pseudogene)
Gene: Small nuclear RNA gene on chromosome 11 (126,214,260 to 126,214,478, reverse strand). Ensembl gene ENSG00000222067.
Homologues: Orthologues: pig U4 (33% identical), dog U4 (32% identical), mouse Gm25806 (32% identical), rabbit U4 (31% identical), guinea pig U4 (27% identical), guinea pig U4 (25% identical). Paralogues in human: RNU4-36P (37% identical), RNU4-15P (36% identical), RNU4-30P (36% identical), RNU4-40P (36% identical), RNU4-44P (36% identical), RNU4-53P (36% identical), RNU4-10P (36% identical), RNU4-84P (36% identical), RNU4-91P (36% identical), RNU4-50P (35% identical), RNU4-90P (35% identical), RNU4-17P (35% identical), and 80 more.